LCE4A (late cornified envelope 4A)
Description:
Precursors of the cornified envelope of the stratum corneum.
Synonyms: LEP8; SPRL4A
Tractability: No criterion of Open Targets' tractability assessment is met for any kind of drug.
Gene: Protein-coding gene on chromosome 1 (152,708,160 to 152,709,434, forward strand). Ensembl gene ENSG00000187170.
Pathways (Reactome):
Developmental Biology: Formation of the cornified envelope
Gene Ontology:
Molecular function: identical protein binding; protein binding
Biological process: epidermis development
Genetic constraint (gnomAD): Loss-of-function variants: 1 observed, 0.23 expected, observed/expected ratio (o/e) 4.35. That is too few expected variants to judge how well the gene tolerates losing a copy. Missense variants: 107 observed, 116.88 expected, observed/expected ratio (o/e) 0.92, 90% interval 0.78 to 1.08. Synonymous variants: 39 observed, 42.93 expected, observed/expected ratio (o/e) 0.91, 90% interval 0.7 to 1.19.
Diseases named in the same sentence as LCE4A in open-access papers:
LCE4A is named in the same sentence as 2 diseases in open-access papers, as found by Europe PMC text mining. Sharing a sentence is not in itself a finding about the gene and the disease. The quoted sentences say what the papers report.
retinopathy (1 paper, 2024). "In GWAS analysis, we found 12 SNPs had a significant association (p < 10-4) with HCQ retinopathy in genes LCE4A, HRNR, OR2T4, NUDT17, CCDC66, PRSS3, PABPC1 and IGHV." (PMID 38548946, 2024).
LCE4A also shares sentences with these, for which no sentence is quoted: candidiasis (1 paper).